BOC (BOC cell adhesion associated, oncogene regulated)
Description:
Together with CDON, forms a coreceptor required for sonic hedgehog (SHH) handoff to its patched receptor (PTCH1 or PTCH2), thereby allowing activation of the smoothened signaling pathway (By similarity). Binds to the dually lipid-modified Sonic hedgehog protein N-product (ShhN) downstream of SCUBE2 carrier and promotes its release to GAS1 (By similarity). ShhN is then directly transferred to patched receptor by GAS1 (By similarity). May also mediate cell-cell interactions between muscle precursor cells, promoting differentiation of myogenic cells (By similarity).
Synonyms: CDON2; Boi
Tractability: Antibody: UniProt places it where antibodies can reach, with high confidence; its Gene Ontology location is reachable by antibodies, with high confidence; UniProt predicts a signal peptide or a membrane-spanning region; the Human Protein Atlas places it where antibodies can reach.
Gene: Protein-coding gene on chromosome 3 (113,210,846 to 113,287,463, forward strand). Ensembl gene ENSG00000144857.
Subcellular location: Cell membrane
Subcellular location (Human Protein Atlas): Nuclear bodies; Plasma membrane; Nucleoplasm
Pathways (Reactome):
Signal Transduction: Activation of SMO; GLI proteins bind promoters of Hh responsive genes to promote transcription; Ligand-receptor interactions
Developmental Biology: Myogenesis
Gene Ontology:
Molecular function: protein binding; protein carrier chaperone
Biological process: axon guidance; cell-cell adhesion; nervous system development; positive regulation of myoblast differentiation; positive regulation of smoothened signaling pathway
Cellular component: plasma membrane; axon; protein-containing complex; axonal growth cone
Genetic constraint (gnomAD): Loss-of-function variants: 74 observed, 113.79 expected, observed/expected ratio (o/e) 0.65, 90% interval 0.54 to 0.79. The upper end of that interval is the gene's LOEUF score, 0.79, which puts it in group 3 of 6, group 1 being the genes least tolerant of losing a copy. Missense variants: 1,301 observed, 1,546.9 expected, observed/expected ratio (o/e) 0.84, 90% interval 0.8 to 0.88. Synonymous variants: 579 observed, 614.04 expected, observed/expected ratio (o/e) 0.94, 90% interval 0.88 to 1.01.
Homologues: Orthologues: chimpanzee BOC (99% identical), macaque BOC (97% identical), pig BOC (89% identical), dog BOC (89% identical), rabbit BOC (89% identical), guinea pig BOC (87% identical), mouse Boc (86% identical), rat Boc (86% identical), tropical clawed frog boc (62% identical), zebrafish boc (49% identical). Paralogues in human: CDON (29% identical), ROBO2 (19% identical), SDK2 (19% identical), ROBO1 (19% identical), SDK1 (19% identical), IGDCC4 (19% identical), PRTG (18% identical), ROBO3 (18% identical), NEO1 (18% identical), DCC (17% identical), HMCN2 (17% identical), MXRA5 (16% identical), and 24 more.
Diseases named in the same sentence as BOC in open-access papers:
BOC is named in the same sentence as 17 diseases in open-access papers, as found by Europe PMC text mining. Sharing a sentence is not in itself a finding about the gene and the disease. The quoted sentences say what the papers report.
holoprosencephaly (4 papers, 2014 to 2021). Holoprosencephaly (HPE) is a complex brain malformation resulting from incomplete cleavage of the prosencephalon, occurring between the 18th and 28th day of gestation, and affecting both the forebrain and face, which results in neurological manifestations and facial anomalies of variable severity. "Impaired function of BOC, CDON, and GAS1 appears to underlie holoprosencephaly, both in humans and in mice." (PMID 29492654, 2018). "Collectively, this phenotype demonstrates both redundancy and individual requirements for Gas1 and Boc during sonic hedgehog transduction in the craniofacial midline and suggests BOC as a potential digenic locus for lobar holoprosencephaly in human populations." (PMID 25063195, 2014).
medulloblastoma (4 papers, 2020 to 2024). A malignant, invasive embryonal neoplasm arising from the cerebellum. "BOC expression was upregulated in pancreatic cancer stroma, and studies have shown that the Shh-binding protein BOC is upregulated in medulloblastomas and induces granule cell precursor proliferation." (PMID 39346724, 2024). "BOC inactivation resulted in reduced proliferation and progression of early medulloblastomas to advanced cancer." (PMID 35631574, 2022). "BOC is a driver of SHH signaling and is associated with granule cell precursor proliferation and medulloblastoma tumorigenesis; inactivation is associated with decreased medulloblastoma progression." (PMID 34667228, 2021). "Overall, inhibition PDGFA, CXCR4, BOC, MET, and NGFR have all shown therapeutic promise in SHH-subgroup medulloblastoma." (PMID 34667228, 2021). "We found that among the selected genes, three of the downregulated genes (BOC, VCAM1, and TP63) followed the same pattern as ERBB4 and showed a higher expression in Group 4 medulloblastomas." (PMID 32316671, 2020). "Next, we moved our attention to genes already related to medulloblastoma based on the literature and validated some of them, such as POSTN, BOC, VCAM1, and TP63 among the downregulated genes and ANKRD1, THBS1, NRG1, PTHLH, and HBEGF among the upregulated ones in DAOY and D283Med cells." (PMID 32316671, 2020).
cancers of the pancreas (3 papers, 2020 to 2024). "Another study reported that loss of Hh ligand co-receptors, GAS1 and BOC, in mouse embryonic and pancreas cancer-associated fibroblasts (CAFs) led to partial suppression of pathway response to SHH and increased angiogenesis." (PMID 32108165, 2020). "The relation between BOC expression and metastasis has been described in non-small-cell lung cancer and cancers of the pancreas and prostate." (PMID 34203581, 2021).
colorectal cancer (2 papers, 2025). A primary or metastatic malignant neoplasm that affects the colon or rectum. "Among these, CDKN2B, BOC, and METRNL showed p-values greater than 5e-8 in the colorectal cancer GWAS data." (PMID 41144378, 2025). "While some studies have reported its upregulation in breast and colorectal cancers, suggesting a potential oncogenic function, others have reported its downregulation in glioma, where it acts as a tumor suppressor by targeting oncogenes such as CORO2A, APC2, WNT7A, and BOC." (PMID 40431607, 2025).
agenesis of the corpus callosum (1 paper, 2014). "Interestingly, the human BOC gene is known to be situated on chromosome 3q13.2 and deletions of 3q13.1q13.3 or 3q13.2q21.3 have both previously been associated with agenesis of the corpus callosum and abnormal facial features." (PMID 25063195, 2014).
breast carcinoma (1 paper, 2021). "BOC mRNA levels in the independent cohort presented a trend towards overexpression in the breast cancers that metastasized to the brain, which was corroborated, in a similar fashion, in the online dataset of 204 primary breast cancers (p > 0.05)." (PMID 34203581, 2021). "The immunohistochemistry results for BOC confirmed the results of the gene expression profiles: BOC was found to be a significantly overexpressed protein in our validation cohort, associated with cerebral metastasis of ER- breast cancer and had not been reported previously." (PMID 34203581, 2021). "Three genes BOC, SPOCK2, and GJD3 were overexpressed in the group of primary breast cancers which developed brain metastasis." (PMID 34203581, 2021). "In the current study, we found that the expression of BOC, SPOCK2, and GJD3 is upregulated in the ER- primary breast cancer samples of patients who developed brain metastases." (PMID 34203581, 2021).
cervical cancer (1 paper, 2024). A primary or metastatic malignant neoplasm involving the cervix. "Additionally, we found that knockdown of BOC or LRP2 inhibits the proliferation of cervical cancer cells." (PMID 39346724, 2024). "Initially, our findings suggest that CLPTM1L may influence cervical cancer cell proliferation through downstream candidate genes BOC and LRP2, while also playing a crucial role in regulating cisplatin-induced apoptosis via DAP1." (PMID 39346724, 2024).
cleft palate (1 paper, 2025). Cleft palate is a fissure type embryopathy that affects the soft and hard palate to varying degrees. "Particularly, three BOC missense variants (p.R407W, p.G436S, and p.D1018N) are identified in three unrelated cases with cleft palate." (PMID 40464334, 2025).
glioblastoma multiforme (1 paper, 2021). "BOC was reported to be overexpressed in patients with glioblastoma multiforme and related to poor survival outcomes." (PMID 34221960, 2021).
cancer (5 papers, 2020 to 2026). A tumor composed of atypical neoplastic, often pleomorphic cells that invade other tissues. "In this context, the aim of this manuscript is to provide an up-to-date overview of BoC system development and their most recent application towards the diagnosis of cancer, infectious diseases, and neurodegenerative disorders." (PMID 33353220, 2020). "Knockdown of BOC markedly inhibited cancer cell migration, without affecting proliferation." (PMID 41930156, 2026).
tumor (5 papers, 2013 to 2026). "BOC cell adhesion-associated, oncogene-regulated (BOC, also known as Brother of CDO [Cell adhesion molecule-Related/Down-regulated by Oncogenes]), a hedgehog-related cell surface receptor, may serve as a biomarker for tumor progression and chemotherapy response." (PMID 41930156, 2026). "The large majority of super enhancers were tumor-specific and enriched for tumor-related genes, such as PAX6, FGFRL1, FGFR1, SKI, and BOC." (PMID 30279357, 2018). "A notable example is that of CDO and BOC, which were initially isolated on the basis of their downregulation by RAS oncogenes in transformed cells, and that were shown to act as tumour suppressors in vitro." (PMID 23667323, 2013). "Examination of main Hh target genes individually shows higher levels of GLI2, PTCH1, SMO, BOC, and HHIP transcripts in the tumor-adjacent tissue as compared to the bulk tumor, further supporting the importance of the tumor-adjacent tissue in the activity of Hh signaling." (PMID 31658643, 2019). "Importantly, both CDO and BOC are downregulated by RAS oncogenes in transformed cells and their overexpression can inhibit tumour cell growth in vitro." (PMID 23667323, 2013). "To date, Hh has not yet to be perceived as a tumour suppressor, although it is noteworthy that human homologs of ihog, CDO, and BOC were initially identified as tumour suppressors." (PMID 23667323, 2013).
BOC also shares sentences with these, for which no sentence is quoted: pancreatic cancer (2 papers); breast tumors (1); Calpainopathy (1); glioma (1); infectious disease (1); non-small cell lung carcinoma (1).